EGFR (epidermal growth factor receptor)
Diseases named in the same sentence as EGFR in open-access papers (continued):
Sharing a sentence is not in itself a finding about the gene and the disease.
glioblastoma (continued). "Studies investigating the expression level and prognostic significance of EGFR in patients with glioblastoma immunohistochemistry." (PMID 40227788, 2025). "EGFR alterations were first described in central nervous system tumors, particularly glioblastoma (GBM)." (PMID 40364160, 2025). "The WHO considers the Epidermal Growth Factor Receptor (EGFR) one of the key biomarkers of glioblastoma (GB)." (PMID 40943631, 2025). "The overexpression of the epidermal growth factor receptor (EGFR) in certain types of prostate cancers and glioblastoma makes it a promising target for targeted radioligand therapy." (PMID 39860082, 2025). "The epidermal growth factor receptor (EGFR) has been reported to be upregulated in several cancers, including glioblastoma." (PMID 39940647, 2025). "We propose that the mutation status of ERRFI1 and the expression levels of MIG6 can serve as additional biomarkers for guiding EGFR‐targeted cancer therapies, including glioblastoma." (PMID 39129344, 2025). "Preliminary analysis on brain sections of model animals with tissue glioblastoma 101.8 by immunohistochemical investigation confirmed the expression of EGFR on tumor cells." (PMID 41473440, 2025). "Epidermal growth factor receptor (EGFR) amplification and mutations are frequently observed in IDH‐wildtype glioblastomas, which are associated with poor prognosis and represent potential targets for molecular therapies." (PMID 40197845, 2025). "Proteomic analyses have revealed alterations in the exosomal proteome of cancer cells, including those from glioblastoma (GBM), where oncogenic proteins like EGFR variant III enhance invasiveness." (PMID 40317075, 2025). "Various studies have shown the improved cytolytic activity of NKG2D CAR-NK cells when incorporated with BiKEs, achieving over 60% lysis in HER2 breast carcinoma cells and increasing glioblastoma cell killing from 11–13% to 32–43% in EGFR/HER2-targeted models." (PMID 41511303, 2025). "Several studies have explored exosome-based drug delivery for glioblastoma treatment, such as curcumin-loaded exosomes and siRNA-loaded exosomes targeting EGFR." (PMID 40427146, 2025). "The association between EGFR alterations and REP in our cohort aligns with the established role of EGFR in glioblastoma aggressiveness and therapeutic resistance." (PMID 41212363, 2025). "Further molecular profiling of 1122 diffuse glioma samples by Ceccarelli and colleagues in 2016 revealed IGFBP-2 protein elevation in glioblastoma with EGFR, P-EGFR and P-Akt, when compared with lower-grade gliomas (2016 CNS WHO grades II and III)." (PMID 40429889, 2025). "Collectively, these results validate the use of ColabFold for accurate modeling of MHC class I peptide complexes and highlight the EGFR p.Ala289Asp-derived epitope as a promising candidate for HLA-A*68:01-restricted immune targeting in glioblastoma." (PMID 41301809, 2025). "CART with bispecific T-cell engager (CART.BiTE) cells were engineered to co-express an EGFRvIII-specific CAR and secrete EGFR-targeting BiTEs, enhancing the elimination of heterogeneous glioblastoma tumors." (PMID 40223940, 2025). "In this study, we provide experimental evidence indicating that the use of a modified anti-EGFR antibody pre-complexed with donor-sourced NK cells represents a major opportunity in glioblastoma settings." (PMID 39996727, 2025). "The choice of dual targeting (EGFR + IL13Rα2) was deliberate: both antigens are frequently co-expressed in glioblastoma, reducing the likelihood of antigen escape—a common failure mode in single-target CAR-T therapies." (PMID 41154636, 2025). "synthesized a series of small molecules as a potential dual‐acting PD‐L1/EGFR inhibitor EP26 against glioblastoma." (PMID 40859900, 2025).
glioblastoma (continued). "The molecular targets and pathways involved in glioblastoma include the epidermal growth factor receptor (EGFR)-mediated PI3K/Akt and MAPK pathways, the PTEN-regulated mTOR/PI3K/Akt pathway, NF-Kb and the JAK/STAT pathway." (PMID 41035668, 2025). "Radiomic features extracted from DTI and other imaging sequences have been shown to correlate with glioblastoma molecular subtypes, including IDH mutation, MGMT methylation, and EGFR amplification." (PMID 40563748, 2025). "In this study, we identify and functionally characterize a novel amplified fusion, MDM2 (exon 1)::PDGFRA (exon 8), mediating resistance to cetuximab in an EGFR-amplified glioblastoma." (PMID 40819143, 2025). "This is reminiscent of truncated EGFR mutant, EGFRvIII, which stimulates downstream signalling in glioblastoma through dimerization with wt-EGFR or unrelated RTKs, such as cMET." (PMID 40044635, 2025). "Serum exosomes were analyzed in patients with glioblastoma, and results of a previous study revealed that EGFR, EGFRvIII and CD63 were expressed at high levels." (PMID 40612948, 2025). "In conclusion, we demonstrated that FDX1 knockdown suppresses cellular radioresistance under severe hypoxia by regulating ATM, DNA-PKcs, Akt, and EGFR expression in the human glioblastoma cell line T98G." (PMID 40244269, 2025). "Our study builds on previous research evaluating targeted therapies against LSD1 or EGFR in glioblastoma, with both similarities and differences in efficacy." (PMID 41497449, 2025). "This mutant form of EGFR, EGFRvIII detected in glioblastoma multiforme, and other types of cancer exhibits enhanced activity due to inability to bind a ligand resulting in impaired endocytosis and constitutive signalling." (PMID 40044635, 2025). "Due to its pivotal role in glioblastoma progression, EGFR has emerged as a compelling therapeutic target." (PMID 39877641, 2025). "The epidermal growth factor receptor (EGFR) is one of the key oncomarkers in glioblastoma (GB) biomedical research." (PMID 39940838, 2025). "For instance, QDs labeled with epidermal growth factor receptor (EGFR) antibodies selectively bind glioblastoma and oligodendroglioma tissues overexpressing the EGFR, allowing a single-cell-level visualization and precise tumor boundary demarcation." (PMID 40870510, 2025). "In a human glioblastoma xenograft model, oncolytic cytomegalovirus expressing EGFR‐redirection H/F complex demonstrated enhanced antitumor efficacy." (PMID 40859900, 2025). "Our study provides new insights into the efficacy of plinabulin against glioblastoma and highlights the potential clinical utility of combining plinabulin with EGFR inhibitors as a chemotherapy strategy." (PMID 39877641, 2025). "For example, in glioblastoma, EGFR amplification accounts for some of the aggressive behavior typically observed, while germline mutations in LRRK2 increase the likelihood of PD in individuals who carry them." (PMID 40806492, 2025). "Various receptor tyrosine kinase (RTK) inhibitors are currently under clinical investigation in patients with glioblastoma, including agents targeting the EphA3 receptor, EGFR, and VEGF." (PMID 40277764, 2025). "In this model, EGFR glioblastoma cells consistently migrate along white matter tracts, blood vessel basement membranes, or beneath subdural sheets." (PMID 40940872, 2025). "Overexpression of EGFR, which plays a critical role in glioma development, is frequently observed in glioblastoma multiforme." (PMID 40075568, 2025). "This study describes a novel, pathogenic MDM2(exon 1)::PDGFRA(exon 8) fusion detected after cetuximab treatment in an EGFR-amplified glioblastoma." (PMID 40819143, 2025). "Targeted therapies focus on specific molecular pathways dysregulated in glioblastoma, including inhibitors targeting EGFR and VEGF pathways, as well as PI3K pathway modulators." (PMID 41009025, 2025).
glioblastoma (continued). "The partial reversal by SC79 further supports that these antitumor effects are mediated through inhibition of the EGFR/Akt/mTOR pathway, suggesting that amlodipine holds significant therapeutic potential against glioblastoma via targeting GSCs." (PMID 41145413, 2025). "A total of 14 studies were included to evaluate the impact of EGFR amplification on survival outcomes in glioblastoma patients, involving 580 patients with EGFR amplification (EGFR-amp) and 1032 patients with wildtype EGFR (EGFR-wt)." (PMID 40331985, 2025). "The diffuse astrocytoma, IDH-wild-type, WHO grade II, as well as the anaplastic astrocytoma IDH-wild-type WHO grade III, will both become glioblastoma IDH-wild-type CNS WHO grade 4 if they feature TERT promoter mutation, EGFR amplification, and/or +7/−10)." (PMID 39057054, 2024). "Applied individually, in in vitro cell-killing assays, these NKAB-EGFR and NKAB-ErbB2 antibodies specifically redirected NKAR-NK-92 and NKAR_RD-IL15-NK-92 cells to glioblastoma and other cancer cells with elevated EGFR or ErbB2 levels." (PMID 38334638, 2024). "In glioblastoma cells, previous studies have established that the epidermal growth factor receptor (EGFR) is overexpressed in approximately 60% of primary cases, associating with more aggressive tumor phenotypes." (PMID 39772250, 2024). "The epithelial growth factor receptor (EGFR) has been a significant target for therapeutic development in glioblastoma owing to the high prevalence of EGFR amplification and its important role as a key survival signalling pathway." (PMID 38275817, 2024). "In glioblastoma cells, the EGFR gene is the most frequently amplified and overexpressed proto-oncogene." (PMID 39772250, 2024). "Additional genetic hallmarks of glioblastoma are telomerase reverse transcriptase (TERT) promoter mutation, epidermal growth factor receptor (EGFR) amplification, and/or +7/−10 chromosomes copy-number alterations." (PMID 39513861, 2024). "The glioblastoma immunohistochemistry phenotype was confirmed by EGFR and cMet gene amplification in the tumor parallel to the detection of HCMV IE and UL69 genes and proteins." (PMID 38553638, 2024). "Previous studies associated LRIG1 with brain cancer, where it inhibits EGFR expression in glioblastoma cells." (PMID 38790164, 2024). "For instance, rs723527, which is associated with epidermal growth factor receptor (EGFR), influences central nervous system cancer and glioblastoma multiforme and participates in white matter microstructure measurements." (PMID 38890579, 2024). "Taken together, our report of the strong sensitivity of EGFR ECD variants to dacomitinib, as well as observed clinical responses of EGFR G598V, prompt additional consideration of dacomitinib for glioblastomas with EGFR ECD mutations." (PMID 38548752, 2024). "In our sample, amplification or mutation of the EGFR gene, as well as amplification of the PDGFRA and KIT genes, potentially leading to their overexpression, were prevalent in HGG IDH—wildtype glioblastoma." (PMID 39684714, 2024). "EGFRVIII and EGFR as CAR T cell targets are exciting as they are commonly amplified in glioblastoma." (PMID 39364321, 2024). "Critical to success is the identification of glioblastoma patient populations that benefit from EGFR inhibitors." (PMID 38396993, 2024). "Glioblastoma, IDH-wildtype is molecularly characterized by TERT promoter (TERTp) mutation, EGFR amplification, or chromosome 7 gain and 10 loss (7 +/10−), in addition to characteristic pathological findings such as necrosis and microvascular proliferation." (PMID 38605367, 2024). "There are additional case reports of EGFR G598V glioblastoma, which also responded to dacomitinib, such that the tumor had a complete response." (PMID 38548752, 2024).
glioblastoma (continued). "These CAR-T BiTE cells have the ability to secrete EGFR-specific BiTEs, which have shown the ability to eliminate heterogeneous tumors in glioblastoma mouse models through recruiting untransduced T cells against wild-type EGFR and redirecting CAR T cells." (PMID 39364321, 2024). "Majority of primary glioblastomas exhibit amplification and activation of the epidermal growth factor receptor (EGFR)." (PMID 39407193, 2024). "Combination therapy is essential for glioblastoma, and epidermal growth factor receptor (EGFR)-activated MR holds great potential." (PMID 39484162, 2024). "Patient 006 in cohort 2 had EGFR-amplified glioblastoma having progressed on 2 prior therapies of standard chemoradiation followed by 11 cycles of adjuvant temozolomide and 1 cycle of an investigational proteasome inhibitor on a clinical trial." (PMID 38680990, 2024). "In glioblastoma cells, combining EGFR inhibition via AG1478 with sodium butyrate, resulted in decreased cell viability with more activity than either agent alone." (PMID 38183103, 2024). "The success of these drugs in brain metastasis of EGFR-driven tumors provides a roadmap for configuring their use to EGFR-driven glioblastomas." (PMID 38396993, 2024). "In glioblastoma, antibody 806 targets epitope 806, which is present in both amplified wildtype EGFR and EGFRvIII." (PMID 38396993, 2024). "EGFR was one of the first biomarkers studied in glioblastoma, and the presence of amplification is almost exclusively seen in glioblastoma, making its detection influential for diagnosis." (PMID 39518074, 2024). "Given the importance of EGFR in the development and progression of glioblastoma, it is an attractive chemotherapeutic target." (PMID 38672566, 2024). "It encodes a new polymeric protein complex called the rolling translation EGFR (rtEGFR) in glioblastoma (GBM)." (PMID 39452835, 2024). "In therapeutic models, EGFR inhibition promotes TNF-α activation in glioblastoma and increases TNF-α-induced lung epithelial cell apoptosis and pulmonary injury." (PMID 38789573, 2024). "Epidermal growth factor receptor (EGFR) elevated the invasive ability of glioblastoma through DOCK1-MLK3 signaling axis." (PMID 38438882, 2024). "Simply inhibiting the tyrosine kinase activity is insufficient to block EGFR action in glioblastoma, as TKIs (tyrosine kinase inhibitors) fail to reduce downstream signaling in clinical trials." (PMID 38672566, 2024). "7MeERT induced the inhibition of the proliferation of various cancer cells similarly to Ertredin and showed higher activity in glioblastoma cells, A431 cells overexpressing EGFR (wild type), and multiple myeloma cells." (PMID 39334963, 2024). "The overexpression of EGFR and consequent activation of the Ras signaling pathway is the dominant oncogenic process in glioblastoma and melanoma cells, respectively." (PMID 39772250, 2024). "The lightcyan module, which closely tracked the abundance of clone 5, was significantly enriched with genes involved in EGFR and NF-kB signaling, as well as genes comprising the proneural subtype of glioblastoma." (PMID 39001492, 2024). "Curcumin leads to dose-dependent antiproliferative effects on glioblastoma cells by inhibiting the overexpression of EGFR upto 30 μM concentration." (PMID 39407193, 2024). "Despite the variety of EGFR inhibitors, glioblastoma-targeting anti-EGFR therapy remains challenging due to the low mutational burden, specific alterations in glioblastoma, and the blood–brain barrier." (PMID 39768176, 2024). "For the treatment of glioblastoma, these are gamma knife therapy, proton beam therapy, tumor-treating fields, EGFR and VEGF inhibitors, multiple RTKs inhibitors, and PI3K pathway inhibitors." (PMID 38891962, 2024).
glioblastoma (continued). "This interaction results in stabilized STAT3-chromatin interactions and subsequent activation of STAT3 downstream signaling, thereby intensifying the oncogenic activity of the EGFR/STAT3 pathway in glioblastoma." (PMID 39160596, 2024). "TRIM24 emerges as an oncogenic transcriptional co-activator in epidermal growth factor receptor (EGFR)-driven glioblastoma." (PMID 39160596, 2024). "Glioblastoma (GBM) commonly displays epidermal growth factor receptor (EGFR) alterations (mainly amplification and EGFRvIII) and TAT-Cx43266–283 is a Src-inhibitory peptide with antitumor properties in preclinical GBM models." (PMID 38507464, 2024). "Epidermal Growth Factor Receptor (EGFR) signaling plays an important role in the prognosis of Glioblastoma multiformes (GBMs)." (PMID 39457021, 2024). "Vasectasia is a newly described, non-angiogenic form of blood vessel formation induced by mesenchymal glioblastoma cells, and driven by endothelial cell responses to extracellular vesicles containing oncogenic EGFR." (PMID 38570528, 2024). "The EGFR protein is frequently overexpressed in up to 90% of glioblastomas, with the most common anomaly being an increased number of copies of the gene by focal gene amplification, which is observed in around 40% of cases." (PMID 39518074, 2024). "MNPs have the capacity to cross the BBB and are covalently attached to antisense oligonucleotides to target glioblastoma cells by suppressing EGFR/EGFRvIII and c-Myc nuclear transcription factors." (PMID 38396993, 2024). "Approximately 57-60% of glioblastomas exhibit alterations in the RTK/PI3K pathway, with EGFR amplification or mutation being the most common, occurring in about 40-50% of cases." (PMID 39439947, 2024). "The use of this antibody followed by computerized tomography (CT) imaging allowed for real-time visualization of EGFR conformation distribution in glioblastoma." (PMID 38396993, 2024). "Data from RNA sequencing analysis, performed in glioblastoma tissue specimens according to the thrombotic phenotype, showed a higher EGFR expression in the group with many thrombi with respect to that with few thrombi." (PMID 39035772, 2024). "Nanomaterials and drug optimizations that overcome the BBB hold promise in targeting EGFR for glioblastoma treatment." (PMID 38672566, 2024). "EGFR ligand in EGFR-amplified glioblastoma was able to activate the tumor suppressor of EGFR, which resulted in the conversion of EGFR oncogenes to oncogenes." (PMID 39689118, 2024). "There is also the need for a delivery mechanism or glioblastoma EGFR-mutant-specific drug to avoid the buildup of antibodies in non-tumor tissue." (PMID 38396993, 2024). "Clusters 1–3 represented glioblastoma cells expressing Nestin, Ki67, EGFR and VEGFA, with cluster 1 showing the most aggressive signature and highest inferred fraction of cells in the G2M cell cycle phase." (PMID 39304781, 2024). "A recent key study demonstrated that PARN activates EGFR-STAT3 signaling to exacerbate glioblastoma malignancy by degrading EGFR-targeting miR-719." (PMID 38689093, 2024). "EGFR amplification has been reported in up to 45% of patients with glioblastoma, and numerous studies have demonstrated the important role of the EGFR/PI3K/AKT/mTOR signaling pathway in glioblastoma progression." (PMID 38315329, 2024). "An in vitro study with glioblastoma cell lines reported AR activation that was mediated by EGFR signaling." (PMID 38233838, 2024). "Glioblastoma cells overexpress epidermal growth factor receptor (EGFR) to varying degrees and have been a target for previous immunotherapies, though with unsatisfactory results." (PMID 38263486, 2024). "A phase III trial treated newly diagnosed patients with EGFR-amplified glioblastoma with depatuxizumab mafodotin, temozolomide, and radiotherapy and found no success in improving OS." (PMID 38396993, 2024).